SLC25A53 (solute carrier family 25 member 53)
Synonyms: MCART6
Tractability: Antibody: UniProt predicts a signal peptide or a membrane-spanning region.
Gene: Protein-coding gene on chromosome X (104,099,214 to 104,157,009, reverse strand). Ensembl gene ENSG00000269743.
Subcellular location: Mitochondrion inner membrane
Gene Ontology:
Molecular function: NAD transmembrane transporter activity
Biological process: NAD transmembrane transport
Cellular component: mitochondrion; mitochondrial inner membrane
Homologues: Orthologues: macaque SLC25A53 (99% identical), chimpanzee SLC25A53 (99% identical), dog SLC25A53 (95% identical), rat Slc25a53 (92% identical), guinea pig SLC25A53 (91% identical), rabbit SLC25A53 (91% identical), pig SLC25A53 (91% identical), mouse Slc25a53 (89% identical), tropical clawed frog slc25a53 (51% identical). Paralogues in human: SLC25A51 (22% identical), SLC25A52 (21% identical), UCP1 (21% identical), SLC25A39 (19% identical), SLC25A21 (18% identical), UCP3 (18% identical), SLC25A12 (17% identical), SLC25A17 (17% identical), SLC25A30 (17% identical), SLC25A40 (17% identical), UCP2 (17% identical), SLC25A28 (17% identical), and 37 more.
Diseases named in the same sentence as SLC25A53 in open-access papers:
SLC25A53 is named in the same sentence as 1 disease in open-access papers, as found by Europe PMC text mining. Sharing a sentence is not in itself a finding about the gene and the disease.
SLC25A53 shares sentences with these, for which no sentence is quoted: myocardial infarction (1 paper).